HDAC2 (histone deacetylase 2)
Diseases named in the same sentence as HDAC2 in open-access papers (continued):
Sharing a sentence is not in itself a finding about the gene and the disease.
tumor (continued). "HDAC2 inhibition was found to stabilize tumor suppression and induce apoptosis in human keratinocyte cells infected with high-risk HPV." (PMID 31892232, 2019). "In this study, we found that NOS1 modifies HDAC2 by S-nitrosylation, resulting in increased tumor metastasis in B16F10 mice." (PMID 31805977, 2019). "Our results suggested that XIAP, RICTOR and HDAC2 either independently or cooperatively contribute functionally to the tumour suppressive effects of miR-500a-5p in CRC cells." (PMID 30737378, 2019). "Upregulation of HDAC2 is frequently observed in human tumor tissues, and knockdown of HDAC2 suppresses tumor cell proliferation and tumor progression." (PMID 31727867, 2019). "HDAC2 silencing further indicated that HDAC2 was significant for mechanical hyperalgesia modulation after the inoculation of tumor cells." (PMID 31324142, 2019). "Here, the authors investigate the role of miR-500a-5p in CRC in vitro and in vivo models and find that miR-500a-5p acts as a tumour suppressor in CRC by targeting the p300/YY1/HDAC2 axis." (PMID 30737378, 2019). "Further, YY1 was also shown to repress the tumor suppressor miR-500a-5p and promotes CRC tumor progression in a p300/YY1/HDAC2 dependent manner." (PMID 31824839, 2019). "Taken together, these results indicate that NOS1-induced S-nitrosylation of HDAC2 promotes lung metastasis primarily by inhibiting tumor lymphocyte infiltration." (PMID 31805977, 2019). "In summary, our study shows that miR-500a-5p is significantly down-regulated in CRC and suppresses CRC tumour growth and metastasis by targeting HDAC2." (PMID 30737378, 2019). "In this study, the inhibition of HDAC2 with an siRNA decreased IFNα responsiveness, while the overexpression of HDAC2 augmented the IFNα response of tumor cells." (PMID 31805977, 2019). "We found that the HDAC2 downregulation significantly promoted tumor growth in nude mice compared to mock MG63 cells with a tumor size of 2,9 ± 0,5 fold greater than those detected in mock MG63 cells." (PMID 30509303, 2018). "It has been recently shown that the carboxylic moiety of lovastatin can bind and chelate the catalytic site of HDAC2, leading to increased p21 expression and inhibition of tumor cell growth." (PMID 29608241, 2018). "Consistent with the in vitro experiments, in xenograft mouse models, silencing TRPS1 significantly reduced both tumor volume and weight, and additional overexpression of HDAC2 rescued this phenotype of xenograft tumors." (PMID 30071870, 2018). "A decrease in HDAC2 markedly inhibits tumor growth, suggesting HDAC2 acts as an oncogene in tumorigenesis." (PMID 30071870, 2018). "HDAC2 implements the transcription repression program by deacetylating H4K16ac and contributes to tumor growth." (PMID 30071870, 2018). "Taken together these results led to a mechanistic scheme in which TRPS1 scaffolding recruits USP4 to de-ubiquitinate and stabilize HDAC2, leading to repression of a set of anti-growth genes and acceleration of tumor growth." (PMID 30071870, 2018). "Nevertheless, our observation that TRPS1 recruits USP4 to de-ubiquitinate HDAC2 extends the current knowledge on the regulation of HDAC2 stability by the ubiquitin system, contributing to tumor growth." (PMID 30071870, 2018). "The study conducted by Marquard and collaborators in cutaneous T-cell lymphoma (CTCL) patients reported a high expression level of HDAC1, HDAC2, and HDAC6, and an association between the levels of HDAC2 and histone H4 acetylation and tumor aggressiveness." (PMID 30096875, 2018). "In vitro and in vivo experiments confirmed that silencing TRPS1 reduced tumor growth, whereas overexpression of HDAC2 restored tumor growth." (PMID 30071870, 2018).
tumor (continued). "Immunohistochemical analyses of paraffin-embedded tumor samples confirmed the presence of HDAC2 in 95% of cells and in all cases tested." (PMID 30509303, 2018). "For example, HDAC2 is highly expressed in tumours and related to p16; by inhibiting HDAC2, p16 activity is promoted and cells are arrested in G1/S." (PMID 29853899, 2018). "The mRNA expression level of HDAC2 in CRC tissues was markedly enhanced compared with non-tumor tissues (P<0.05)." (PMID 28538837, 2017). "The expression levels of the core genes RAD21, HDAC2, and CDK1 were increased in HCC tissues compared with adjacent non-tumor tissue, and their expression levels were associated with the OS of HCC patients." (PMID 28434945, 2017). "HDAC2 was expressed in the cytoplasm of tumor cells and was overexpressed in HCC tissues (Wilcoxon test, P < 0.001)." (PMID 28434945, 2017). "Together, these findings suggest that pharmacological inhibition of HDAC1 and HDAC2 is sufficient for anti-tumor activities in AML." (PMID 28060870, 2017). "In conclusion, HDAC2 was up-regulated in CRC tumor tissues and down-regulated HDAC2 significantly inhibited cell proliferation in CRC cells." (PMID 28538837, 2017). "It was recently demonstrated that selectively inhibiting HDAC1 and HDAC2 chemically decreases the tumor growth of SHH-MB in a murine model by inhibiting the Hedgehog pathway (Hh), which is further linked to an increase in GLI1 acetylation." (PMID 29099739, 2017). "HDAC2 played an activation role in tumor growth, whose expression is upregulated and inversely associated with miR-31 levels." (PMID 29333444, 2017). "Initial genetic dissection of the role of specific HDACs in murine models has revealed that HDAC1 and HDAC2 play redundant and essential roles in tumor cell growth in vitro and in vivo." (PMID 28060870, 2017). "Here, we show that Hdac1 and Hdac2 have tumor-promoting roles in both Eμ-myc tumorigenesis and tumor maintenance." (PMID 27886239, 2016). "We then monitored tumor-free survival by KPLM analysis in mice having different combinations of Hdac1 and Hdac2 alleles." (PMID 27886239, 2016). "Our findings demonstrate that loss of Hdac1 and Hdac2 has a direct impact on Eμ-myc tg B cells and demonstrate a critical pro-oncogenic role of Hdac1 and Hdac2 in Eμ-myc tumor progression." (PMID 27886239, 2016). "In order to discriminate between indirect B cell developmental defects and direct effects of Hdac1 and Hdac2 ablation, we investigating the role of Hdac1 and Hdac2 in existing tumor cells." (PMID 27886239, 2016). "We demonstrate that Hdac1 and Hdac2 have a pro-oncogenic role in both Eμ-myc tumorigenesis and tumor maintenance." (PMID 27886239, 2016). "This transplantation assay clearly demonstrates that conditional ablation of both Hdac1 and Hdac2 directly impacts on existing tumor cells and delays tumor appearance." (PMID 27886239, 2016). "CCA tissues had higher expression compared with corresponding matched non-tumor tissues (27.85%, 30.38%, and 32.91% for HDAC2, HDAC3 and HDAC8, respectively; χ2 =10.505, 10.327, 6.609; P<0.05)." (PMID 27705912, 2016). "In conclusion, our results demonstrate that Hdac1 and Hdac2 promote tumor initiation and progression in Eμ-myc mice and that they impact on proliferation and apoptosis." (PMID 27886239, 2016). "Our transplantation experiment clearly demonstrates that conditional ablation of both Hdac1 and Hdac2 has a direct impact on existing tumor cells, since we observed significantly delayed tumor appearance." (PMID 27886239, 2016). "Our results describe the pro-oncogenic roles of Hdac1 and Hdac2 in Eμ-myc tumorigenesis and tumor maintenance and support the clinical use of HDACis." (PMID 27886239, 2016).
tumor (continued). "Non-invasive bioluminescence imaging revealed significant reductions in xenograft tumour growth with HDAC2 expression level reduced to <50% in treated animals." (PMID 27283986, 2016). "Our observed profiles for target engagement therefore corroborate the proposed link between HDAC1 and HDAC2 activities in tumour cell proliferation and inhibition of apoptosis." (PMID 26631872, 2015). "Here we show that HDAC2 enhances NF-κB-dependent gene expression in tumor-derived cell lines and in primary cells." (PMID 25704882, 2015). "To evaluate protein expression of the putative target HDAC2 in a large set of primary MB tumor samples, we performed immunohistochemistry (IHC) for HDAC2 on a tissue micro-array (TMA) with n = 142 MB samples." (PMID 25853389, 2015). "Mean mRNA transcription levels of PA for HDAC7 and HDAC2 were higher when compared to their counterpart biopsies taken at the tumor periphery (p = 0.0346, 0.0053, respectively)." (PMID 25275504, 2014). "In a recent study, Niegisch and colleagues were able to show upregulation of HDAC-2 mRNAs in a subset of tested tumours compared to normal urothelium." (PMID 24624923, 2014). "The class I histone deacetylase HDAC2 is frequently overexpressed in human tumor tissues, and over-expression of HDAC2 induces tumor cell proliferation, blocks apoptosis and promotes tumor progression." (PMID 24952595, 2014). "For HDAC-1 40% of the tumours showed high expression levels, for HDAC-2 42% and for HDAC-3 even 59%." (PMID 24624923, 2014). "Although the post-transcriptional interplay between YY1 and c-MYC and between YY1 and HDAC2 both favour tumour progression, the former activates the fast cell cycle/pluripotency genes, and the latter represses differentiation/fast cell cycle inhibitor genes." (PMID 25115389, 2014). "HDAC1 and HDAC2 have been shown to be crucial for cell proliferation and are therefore considered as promising targets for anti-tumour therapy." (PMID 24240174, 2013). "Previous studies have shown that RFFL and HDAC2 are known to also promote tumor formation by inhibiting the apoptosis process, whereas EIF3H is known to increase cell proliferation, growth and survival and inhibit the apoptosis process." (PMID 24377043, 2013). "Given that these chromatin alterations occur in the diffuse field are known to occur in the tumor, we then assessed the expression of HDAC2 and chromatin nano-structure using TEM in the azoxymethane (AOM)-treated rat model for early CRC." (PMID 23724067, 2013). "In this study, we showed that targeted-disruption of HDAC2 resulted in reduction of both tumor cell growth and de novo DNA synthesis in Hep3B cells." (PMID 22132221, 2011). "Since our results suggest that transient knockdown of HDAC2 exerts potent anti-tumor activity, we next investigated if sustained suppression of HDAC2 can attenuate tumorigenic potential of HCC cells in vitro and in vivo." (PMID 22132221, 2011). "In three cases, additional cytoplasmic positivity, exclusively seen in HDAC2 immunostainings, was observed in a minority of tumour cells." (PMID 18212746, 2008). "Aberrant expression of HDAC1, 2, 3 and 6 has been observed in various tumor types, and HDAC2-mutant mice display reduced tumor development." (PMID 18789133, 2008). "Our findings are supported by a significant lower probability of DFS for patients with HDAC2 high tumours when compared with patients with HDAC2 low tumours as calculated by the respective Kattan nomogram." (PMID 18212746, 2008). "Notably, the expression of HDAC1 and HDAC2 was comparable between ALK+ tumor cells and other immune cells, including T cells, B cells, and NK cells, suggesting that class I HDACs are abundant in normal and malignant immune-cell subsets." (PMID 40175628, 2025). "This suggests that combining anti-PD-L1 immunotherapy with HDAC2 inhibitors could attenuate tumor angiogenesis in UM, offering a novel therapeutic approach." (PMID 40573881, 2025).
tumor (continued). "Previous studies have shown that HDAC inhibitors can suppress the activity of class I HDACs, including HDAC2, inducing cell cycle arrest, apoptosis, and DNA damage in BCa cells, thereby impairing tumor progression and overcoming resistance to PARP inhibitors and cisplatin." (PMID 41408324, 2025). "Furthermore, the aberrant upregulation of HDAC2 mRNA in tumor samples was further confirmed using the UALCAN database and a BCa-related GEO dataset (GSE133624)." (PMID 41408324, 2025). "Importantly, we also discovered that selective HDAC2 inhibitor effectively ameliorates HCC malignancy by reducing tumor volume, significantly inhibiting HCC tumor formation and attenuating HCC autophagy in vivo." (PMID 39147759, 2024). "Comparing HDAC2 expression in tumours from patients with and without liver metastasis and a survival analysis association suggested HDAC2’s potential role in CRC liver metastasis." (PMID 38255946, 2024). "Moreover, compared to 5‐FU and oxaliplatin alone, combining the HDAC2‐selective inhibitor with the regimen resulted in significantly reduced tumour burden." (PMID 38804602, 2024). "Moreover, high HDAC2-expressing tumors are depleted with immune-related processes, and HDAC2 expression correlates with tumor immunosuppressive microenvironments." (PMID 39063083, 2024). "Furthermore, we looked at the levels of chemoattractants in all tested tumor types regarding HDAC2 or HDAC7 expression and observed that HDAC7 upregulation significantly associates with elevation of chemokines and their recognizing receptors." (PMID 39063083, 2024). "Similarly, HDAC2 is generally categorized as a proto-oncogene due to its involvement in epigenetic modulation, contributing to oncogenesis through the repression of tumor suppressor genes." (PMID 38794205, 2024). "Moreover, inducible shHDAC2 HCCLM3 xenografts showed a considerably reduced tumor growth rate following HDAC2 knockdown." (PMID 38890388, 2024). "HDAC2 has been reported to have tumor-promoting properties in various malignancies, such as AML." (PMID 38822351, 2024). "Recent research has demonstrated that inhibition of HDAC2 can induce anti-tumor immune regulation." (PMID 37716965, 2023). "HDAC2 scores also differed in samples with different tumor sizes and stages." (PMID 37171044, 2023). "miR-500a-5p displayed a tumor suppressor role in CRC by targeting the p300/ YY1/HDAC2 axis." (PMID 36968022, 2023). "Additionally, overexpression of HDAC2 was significantly correlated with high tumor grade, positive lymph node status, and poor prognosis." (PMID 37764768, 2023). "HDAC2 may also be a potential biomarker for the prognosis of tumor progression in squamous cell carcinoma of the oral cavity, esophageal squamous cell carcinoma, gallbladder carcinoma, and breast carcinoma." (PMID 37834214, 2023). "In addition, the results of our TMA analyses of a cohort of CRC patients strengthened our in silico data, as we found that high levels of HDAC2 expression were related to tumor tissues mainly localized in the proximal colon and with greater vascular invasion." (PMID 37046620, 2023). "In contrast, the increase in HDAC2 and B2M mutants in CRC appeared to be associated with a differentiated CD4+ Th2 subpopulation, which could affect tumor promotion." (PMID 37046620, 2023). "Therefore, inhibition of HDAC2 in combination with PD-1/PD-L1 blockade is a new strategy for tumor immunotherapy." (PMID 37554324, 2023). "Piezo1 could also upregulate the expression of histone deacetylase 2 (HDAC2), which suppresses Rb1 via epigenetic silencing, thereby expanding MDSCs and conferring a tumor immunosuppressive microenvironment." (PMID 36230880, 2022). "Besides, HDAC2 knockdown dramatically reduced the capacity of tumor-sphere formation in HDAC2 knockdown GSCs and induced apoptosis by caspase-3, Bax, and Apaf-1." (PMID 35260183, 2022).
tumor (continued). "Furthermore, we identified upregulated DEGs in TN tumours including drug targets histone deacetylase enzymes (e.g. HDAC1, HDAC2, and HDAC11) implicated in the epigenetic regulation of gene expression." (PMID 36220861, 2022). "Although we showed that HDAC2 inhibitors obtained good results in inhibiting tumor growth in cell and animal experiments, HDAC2 is highly homologous to HDAC8, which might result in unexpected side effects due to the paninhibition of HDAC." (PMID 35974388, 2022). "The expression levels of HDAC2 and EZH2 were significantly higher in multiple tumor types, indicating that HDAC2 and EZH2 may play important roles as oncogenes." (PMID 35892859, 2022). "Importantly, HDAC2 knockdown also inhibited the tumor-sphere formation of GSCs, indicating that the survival of GSCs was directly regulated by HDAC2 expression level." (PMID 35260183, 2022). "Thus, the aim of our study is to examine the expression of HDAC-2 immunohistochemically in specimens derived from BC tissue and its correlation to the clinicopathological features of the tumor and patient prognosis." (PMID 36294811, 2022). "The result suggested that EEF1E1 and HDAC2 were associated with the progression of tumors where they show significant correlation with grade, stage, and T stage (P < 0.05), and the expression levels of EEF1E1 and HDAC2 were significantly higher in tumor tissue than in normal tissue." (PMID 36189258, 2022). "Additionally, HDAC-1 was associated with increased tumor size, HDAC-6 with mitotic index, and HDAC-2 with epithelioid cell morphology and presence of tumor-infiltrating lymphocytes, both parameters of adverse prognosis." (PMID 34638249, 2021). "Moreover, HDAC2 also promoted IFNγ-induced PD-L1 expression to enhance antitumor immunity and tumor proliferation and metastasis." (PMID 34993131, 2021). "HDAC-2 expression was associated with tumor depth of invasion, while lack of correlation between HDAC-1 and -3 with any of the clinicopathological parameters was noted." (PMID 34441281, 2021). "Nevertheless only HDAC-2 expression was correlated with poor tumor grade of differentiation." (PMID 34441281, 2021). "For example, the expression level of HDAC2 is negatively related to tumor stemness (data based on RNA expression) (p = 0.035), and the higher the expression level of HDAC2, the more stromal cells (p < 0.001) instead of immune cells in the tumor microenvironment." (PMID 34308568, 2021). "In contrast, 70% (106/179) of tumours had moderate or high HDAC2 expression." (PMID 34439236, 2021). "In addition, HDAC2 knockout retarded tumor growth, metastasis, and decreased PD-L1 production in vivo." (PMID 34365463, 2021). "Taken together, these results suggest that HDAC2 may be a tumour metastasis‐promoting oncogene, and this process was closely connected with EMT." (PMID 33325150, 2021). "Further validated by tumor xenografts in mice, depressed HDAC2 was anti-tumorigenic in ESCC." (PMID 33926524, 2021). "Epigenetic changes through micro RNAs and decreased DNA deacetylation by histone deacetylase type 2 (HDAC2), may also affect tumor growth." (PMID 33986726, 2021). "On the other hand, oesophageal adenocarcinoma was slightly associated with the expression of HDAC-2, in terms of a more aggressive tumor behavior, lacking, however, a statistically significant prognostic value." (PMID 34441281, 2021). "Indeed, to our knowledge, besides HDAC2, the only enzyme controlling acetylation/deacetylation of proteins regulated by nitrosylation in tumor cells is the class IIb HDAC6." (PMID 34947954, 2021). "HDAC2 inhibition with SAHA re-localised HDAC2 to the cytoplasm and induced expression of PIK3IP1, which correlated with an improved prognosis for mice bearing ARID1A-mutated tumours." (PMID 33941852, 2021).